KRAS (KRas proto-oncogene, GTPase)
Diseases named in the same sentence as KRAS in open-access papers (continued):
Sharing a sentence is not in itself a finding about the gene and the disease.
colon carcinoma (continued). "Several studies have focused on immune modulation by oncogenic KRAS and checkpoint inhibitors in lung, pancreatic, and colon cancers, which are reviewed elsewhere." (PMID 35014625, 2022). "Third, vitamin C activates pyruvate dehydrogenase, then modulates the TCA cycle and the mitochondrial metabolism in KRAS mutant colon cancer." (PMID 35956413, 2022). "Assuming the high prevalence, in stage II and III, of microsatellite instability (MSI) in KRAS-mutated colon cancer, the evaluation of both BRAF and KRAS mutations in MSI colon cancers is useful for prognosis." (PMID 35456940, 2022). "In contrast, human cancer cells with oncogenic KRAS mutations (HCT116 and SW620 colon cancer cells, A549 lung and MDA-MD-231 breast cancer cells) were much less sensitive to this MEK inhibition." (PMID 35899070, 2022). "DNA isolated from wild-type KRAS and mutant KRAS (G12D) human colon cancer cell lines was also used for optimization experiments." (PMID 35200357, 2022). "In women, a role of KRAS mutations in the etiological pathway between adiposity and colon cancer is suggested, and of PIK3CA mutations between physical activity and colon cancer." (PMID 35546360, 2022). "In our study, two colon cancer cell lines with mutant KRAS (HCT116 and LoVo), and one with wild-type KRAS (HT29) were screened for anti-colon cancer activity." (PMID 35889255, 2022). "PP was also shown to synergize with the KRAS inhibitor salirasib in a WNT-dependent manner, describing a potentially actionable targeted combination of PP and salirasib in KRAS-driven colon cancers." (PMID 36552005, 2022). "Further analysis revealed that reduced tumor growth mediated by specific silencing of the convertase Furin in KRAS or BRAF mutated-induced colon tumors was associated with reduced expression of LGR5 and NANOG compared to wild-type KRAS and BRAF tumors." (PMID 35267511, 2022). "Studies found that inhibition of PAK4 and PAK1 suppresses the KRAS and BRAF mutation in colon cancer in vitro." (PMID 35409064, 2022). "Microsatellite instability-high (MSI-H), deficiency of mismatch repair genes, KRAS and BRAF mutations, and CpG island methylation are more common in right colon cancer than that in left colon cancer." (PMID 35143566, 2022). "Given that KRAS and BRAF mutations are generally mutually exclusive, genetic alterations of KRAS and BRAF were likely to occur in different colon tumors, implying that right-sided colon tumors are predisposed to harbor KRAS-BRAF pathway mutations." (PMID 36439454, 2022). "Results of qPCR suggested that the levels of GJB6 were distinguished according to the status of KRAS-mutation, though we didn’t detect the signals of NTNG1 in colon cancer cell lines." (PMID 35774610, 2022). "Several of the chemotherapeutics were reported to kill selectively colon cancer KRAS mutant cells, in particular drugs targeting DNA topoisomerases, such as camptothecin derivatives and anthracyclines such as doxorubicin." (PMID 36048281, 2022).
colon carcinoma (continued). "Reactivation of ERK and AKT has been shown to drive drug resistance to AUY922 in BRAF mutated colon cancer and to STA-9090 in KRAS-mutant non-small cell lung cancer." (PMID 35327426, 2022). "Cetuximab selection was carried out in SW48 colon carcinoma cells (wild-type KRAS), using 100 nM cetuximab." (PMID 33445730, 2021). "The first study on AS in CRC revealed that c-Ki-ras (KRAS), a protein-coding gene, mutates at splice acceptor site and produces two transcript variants with exon 4A included or excluded in SW480 colon carcinoma cell lines." (PMID 34330892, 2021). "Oncogenic KRAS is a key driver of CRC progression from premalignant colon adenomas to stage I colon carcinomas, and it acts as an activator of CSCs in tumours." (PMID 33802849, 2021). "Two recent studies reported enhanced survival when combining the KRAS G12C inhibitors with anti-PD-1 immune checkpoint blockade in an immunotherapy sensitive syngeneic KRAS G12C mutant CT26 colon carcinoma subcutaneous tumour model." (PMID 34625563, 2021). "In contrast, another study showed that BMP4 was involved in the suppression of colon cancer cell growth and that the activated KRAS down-regulated BMP4 via the ERK pathway." (PMID 33982211, 2021). "Despite activating the same pathway, BRAF mutant tumors have distinct expression signatures from KRAS mutant tumors in colon cancer." (PMID 34214079, 2021). "We used mouse AK organoids established from colonic tumors developed in mice carrying Villin-CreERT2/+, lsl-KrasG12D/+, and ApcΔ716/+ alleles, since APC and KRAS mutations were observed in >80% and >40% of CRC, respectively." (PMID 34262603, 2021). "In support of the previous assumption, it has been shown that oncogenic KRAS promotes ROS generation in colon cancer cells (HCT116 KRASG13D and SW480 KRASG12V) through the signalling cascade p38/PDPK1/PKCδ/p47phox/NOX1." (PMID 33691728, 2021). "For example, tumour-derived EVs can modulate local growth via autocrine transfer of mutant KRAS proto-oncogene to wild type KRAS-expressing colon cancer cells." (PMID 33981316, 2021). "The effects of FTS-inhibited KRAS on the character, composition and uptake of exosomes were investigated in our study, to verify the link between KRAS activities and colon cancer cells-derived exosomes." (PMID 33466836, 2021). "APC mutations in the Wnt/β-catenin pathway and KRAS mutations, the major form of RAS, are frequently found in colon cancer." (PMID 34203665, 2021). "Kirsten rat sarcoma viral oncogene (KRAS) is located downstream of EGFR signals, and KRAS mutations lead to its constitutive activation, which makes advanced colon cancer less responsive to anti-EGFR monoclonal antibodies such as cetuximab and panitumumab." (PMID 34221952, 2021). "While KRAS has been, until recently, seen to be undruggable and the new KRAS inhibitors target only the less frequent mutation G12C, several BRAF and MEK kinase inhibitors have been developed and tested also in colon cancer patients." (PMID 34885128, 2021).
colon carcinoma (continued). "A combination of 5-FU and an MEK inhibitor in sequence has shown synergistic effects in KRAS or BRAF mutant colon cancer models, compared to monotherapy." (PMID 34946546, 2021). "Experiments carried out in colon cancer cell lines (DLD1 and HCT-116) mutated for KRAS have shown that a knock-out or -down of KRASMUT cells impaired the hypoxic induction of HIF-1α." (PMID 33691728, 2021). "Another study showed that incorporating microsatellite instability (MSI), BRAFV600E, and KRAS mutation status into the OS model through TNM staging improves the ability to precisely prognosticate in stages II and III colon cancer." (PMID 34440092, 2021). "miR145, an inhibitor of the embryonic stem cell program, was found to counteract the effects of mutant KRAS by suppressing malignant growth and promoting the differentiation of mutant KRAS colon cancer cells." (PMID 33802849, 2021). "KRAS wild-type colon cancer with EGFR expression greater than the median was predicted to be more resistant to Cetuximab (p < 0.0001)." (PMID 34548481, 2021). "used flow cytometry and immunohistochemistry to look at changes in the TME upon KRAS G12C inhibition in the immunogenic subcutaneous colon cancer model CT26." (PMID 34625563, 2021). "As it has been described, KRAS and BRAF mutations differentially regulate the hypoxic induction of HIF-1α and HIF-2α in colon cancer." (PMID 33664850, 2021). "The current study demonstrated that the inhibition of KRAS by FTS stimulated higher exosome secretion from colon cancer cells, possibly as a stress response to the drug intervention." (PMID 33466836, 2021). "The role of vitamin C in the clinical management of hypoxic KRAS mutant colon cancer and importance of normal plasmatic vitamin C (AA) levels in those patients should be reassessed." (PMID 33664850, 2021). "In a future study, it will be necessary to verify the effect of eupatilin in colon cancer cells with mutations in genes such as APC, β-catenin, and KRAS." (PMID 34203665, 2021). "Colon cancer cells expressing mutant KRAS have been shown to enhance the invasiveness of wild-type KRAS cells via exosomes released by the mutant cells." (PMID 34576294, 2021). "A genome-wide genetic rescue screen led to the identification of YAP1 as a survival mechanism in the HCT-116 KRAS dependent colon cancer cell line upon suppression of KRAS." (PMID 34680229, 2021). "In an orthotopic mouse colon cancer model, elemene and cetuximab combination treatment inhibited tumor growth and lymph node metastasis in a KRAS mutant, inhibiting EMT." (PMID 34641334, 2021). "Oncogenic KRAS or BRAF addiction has been found in lung and colon cancers and melanomas, where KRAS or BRAF is frequently mutated." (PMID 33793658, 2021). "In an orthotopic murine colon cancer model, treatment with cetuximab alone increased the tumor volume and lymph node metastases, indicating that KRAS mutant CRC cells exhibit resistance to cetuximab." (PMID 34641334, 2021). "KRAS, APC, and β-catenin mutations in colon cancers have been associated with poorer survival and increased tumor aggressiveness." (PMID 33917100, 2021). "Clinicopathological characteristics according to KRAS and NRAS mutations status in 210 colon cancer patient." (PMID 33784337, 2021). "Results reveal an improved response by combinatorial treatment in some defined molecular subgroups and potential alternative treatment options in KRAS- and BRAF-mutated colon cancer." (PMID 34885128, 2021). "One example of this is anti-epidermal growth factor receptor therapies for wild-type KRAS colon cancer, which have demonstrated a preferential survival benefit for left-sided cancers." (PMID 34650170, 2021). "Quercetin possesses activities against colon cancer with mutant-type KRAS through JNK-pathway regulation; such activity results are very promising since KRAS is considered undruggable." (PMID 34744708, 2021).
colon carcinoma (continued). "Previous studies mainly focused on identifying characteristic gene expression patterns of BRAFV600E-mutated colon cancer by examining differences between oncogenic BRAF vs. either the KRAS mutation or double wild-type BRAF/KRAS." (PMID 34201061, 2021). "The oncogenic insulin-like growth factor 2 mRNA-binding protein 1 (IMP1) has been previously shown to regulate KRAS mRNA expression in colon cancer cells, possibly through its ability to bind to the KRAS transcript." (PMID 32369483, 2020). "Analysis of colon cancer cell lines revealed that KRAS G12V induces HIF1A hypoxia sensor transcription and, in turn, overexpressed HIF1A or hypoxia activates KRAS signaling." (PMID 32545208, 2020). "Further subgroup analysis found that KRAS MT patients had worse CSS than KRAS WT patients among stage III or stage IV CRC patients or patients with left side colon cancer or rectal cancer." (PMID 32547859, 2020). "Colon cancer was shown to be the results of chromosomal instability resulting in the activation of proto-oncogene KRAS." (PMID 33225921, 2020). "Tumor molecular markers, such as CpG island methylator phenotype (CIMP) status; driver gene mutations, such as KRAS and BRAF; and tumor immune microenvironment, have been linked to different recurrence risks among stage III colon cancer patients." (PMID 33071795, 2020). "Both KRAS and PIK3CA mutations were associated with poor prognosis and chemoresistance of colon cancer patients." (PMID 33197880, 2020). "There is a need to further investigate the predictive value of KRAS for immune activity in colon cancer." (PMID 33254149, 2020). "Although they are yet to be tested in GC, KRAS inhibitors have been used successfully in lung and colon cancer patients." (PMID 32664343, 2020). "RAS, KRAS, and BRAF mutations were found to vary significantly by tumor location, occurring more frequently among right‐sided colon tumors than left‐sided colon tumors." (PMID 31856410, 2020). "This study aimed to evaluate the KRAS gene in colon cancer tissues obtained from patients with type 2 diabetes mellitus (T2DM)." (PMID 32939513, 2020). "Researchers found that the emergence of KRAS mutant clones is the second mechanism of colon cancer resistance through the single-cell analysis of CTC in patients with colon cancer." (PMID 33292625, 2020). "We report here, for the first time, that grifolin, neogrifolin and confluentin suppressed KRAS expression in human colon cancer cells." (PMID 32369483, 2020). "Among the colon cancer cell lines, six (SW403, SW116, SW480, SW1463, MICOL29 and SW620) were characterized by a mutation in exon 2 of the KRAS gene and two (CO115 and HT-29) by the V600E mutation in the BRAF gene." (PMID 33233823, 2020). "The extracts were tested using two cell lines representative of the main genetic profiles of human colon cancer, HCT116 (KRAS mutated) and RKO (BRAF mutated) and IC50 and IC25 values determined." (PMID 32806531, 2020).
colon carcinoma (continued). "Treatment of colon-cancer challenged mice with rAF-IL12 had resulted in the downregulation of KRAS, BRAF, and MAPK1 expression in tumour while previous studies had reported that expression inhibition of these genes would improve patient survival." (PMID 32612457, 2020). "The four primary colon tumors presented with four different KRAS genotypes, one of them with a wild-type and three with pathogenic variants, without overlap." (PMID 32560038, 2020). "Specifically, mutant KRAS is a driver oncogene in pancreatic, lung and colon cancers and in a small fraction of breast tumors." (PMID 33193348, 2020). "Grifolin, neogrifolin and confluentin suppress KRAS expression in colon cancer cells, a novel bioactivity for these compounds." (PMID 32369483, 2020). "For example, exosomes isolated from mutant KRAS-expressing colon cancer cells enhanced the invasiveness of KRAS wild-type recipient cells." (PMID 33168028, 2020). "Quercetin, a dietary flavonoid, was reported to induce human colon cancer cell apoptosis by inhibiting the NF-κB pathway and inducing apoptosis in KRAS-mutant CRC cells via JNK signaling pathways." (PMID 33294000, 2020). "Previously, we had reported the anti-tumor effect of miR-143 within an immunodeficient xenograft mouse model by targeting KRAS and its effector molecules in bladder cancer cells, bladder cancer cells, and colon cancer cells." (PMID 32370060, 2020). "The effect of expression of FOSL2 and colon cancer cells possessing wild-type KRAS in terms of sensitivity is yet to be studied." (PMID 31245295, 2019). "Among them, sixteen studies with 5, 835 patients provided the data of KRAS status in colon cancer, with 3961 LCC patients and 1874 RCC patients, respectively." (PMID 30917791, 2019). "Our results suggest that combination of KRAS inhibition and trametinib strikingly suppresses cell viability of KRAS mutant colon cancer cells." (PMID 30833665, 2019). "The results we present here suggested that oncogenic mutant KRAS increases TNT-mediated cross-talk between colon cancer cells and that these cells harness these TNTs to further disperse KRAS molecules to other wild-type KRAS colon cancer cells." (PMID 31247990, 2019). "A recent study showed that high-dose vitamin C selectively kills colon cancer cells carrying KRAS (KRAS proto-oncogene, GTPase) or BRAF (B-Raf proto-oncogene, serine/threonine kinase) mutations." (PMID 31905996, 2019). "The kinetics of ctDNA derived from each cancer type were monitored targeting BRAF V600R (melanoma) and KRAS G13D (colon cancer), specifically reflected the status of the patient’s tumours." (PMID 31727009, 2019). "It is well known that aberrant activation of MAP kinase pathways induced by activating mutations in KRAS or BRAF contributes to abnormal cell growth and functions as a critical mechanism leading to tumorigenesis of colon cancer." (PMID 31409052, 2019). "Our study provides new insights into the mechanisms of resistance to KRAS ablation, and suggests novel strategies for the treatment of KRAS-mutant colon cancers." (PMID 30833665, 2019). "Analysis of additional KRAS-driven tumor types demonstrated a similar initial survival trend in KRAS mutant colon cancer, where KRAS was also readily observed proximal to these SNAREs in a series of patient tumor specimens." (PMID 31712554, 2019). "In conclusion, our investigation of the intercellular transfer of KRAS via TNTs has elucidated a novel mechanism by which a tumor-driving mutant protein can be trafficked and distributed among cancer cells, in this case colon cancer cells specifically." (PMID 31247990, 2019). "In vitro and in vivo results suggests that inhibition of MEK nuclear localization by trametinib synergizes with KRAS knockdown or deltarasin treatment in suppressing the viability of KRAS mutant colon cancer cells." (PMID 30833665, 2019).